CD24 (CD24 molecule)
Diseases named in the same sentence as CD24 in open-access papers (continued):
Sharing a sentence is not in itself a finding about the gene and the disease.
tumor (continued). "The heat stable antigen or small-cell lung carcinoma cluster 4 antigen (CD24), a heavily glycosylated glycosylphosphatidylinositol-anchored surface protein, is the ligand for Siglec-10 on tumor-associated macrophages (TAMs) and induces the inhibition of phagocytosis." (PMID 33333862, 2020). "Interestingly, STAT3-mediated Nanog expression can regulate self-renewal and tumor initiation in CD24+ LCSCs." (PMID 33117795, 2020). "Although the mechanisms by which the presence of CD24+ cells contributes to cell heterogeneity within the tumor is unknown, it is interesting to appreciate that the CD24+ cell population has a more pro-inflammatory SASP." (PMID 32478091, 2020). "Besides, Davidson and colleagues demonstrated that tumor cells collected from OC peritoneal fluids exhibited higher levels of CD24 than solid tumors, suggesting an enrichment of CSCs." (PMID 32257947, 2020). "Flow cytometry analysis of protein expression profile of unmodified TMVs showed that TMVs express tumor and immune cell markers such as cancer stem cell markers (CD24 and CD44), co-stimulation (CD80 (B7-1)), immunosuppression (CD47, PD-L1), and innate immune cells (Gr1)." (PMID 32295135, 2020). "Initially, the patient with stemness gene amplifications had a high concentration of EpCam+CD44+CD24– tumor stem cells – more than 50%, while patient Ti41749/17 had a level slightly above 30% and a two-fold higher concentration of EpCam+CD44hiCD24– cells (37% compared with 18%)." (PMID 32523653, 2020). "The interaction between CD24 and Siglecs is considered to be the complex of placental immunosuppressive response, and a great number of placental cells and molecular markers have been evaluated for their role in tumor immune escape." (PMID 32765491, 2020). "In addition, TQ significantly decreased the T47D associated stem cell clone (CD44+/CD24) by 19.9 ± 0.8%, while PTX caused a 9.9 ± 0.2% decrease in the tumor-associated stem cell clone." (PMID 31968657, 2020). "However, even though many studies suggest a direct role of CD24 in tumor growth, invasiveness and migration, and the formation of metastases, its potential molecular mechanisms are not fully understood." (PMID 33260974, 2020). "In TNBC, CD24 affects chemosensitivity according to drug type and may regulate the drug sensitivity of tumor cells, in part through modulation of cellular autophagy status." (PMID 32394616, 2020). "We have demonstrated that CD24-Alexa Fluor 680 can positively identify tumor lesions through non-invasive imaging at an early stage of the disease, detect early metastatic dissemination, and allow the longitudinal evaluation of tumor progression and treatment efficacy." (PMID 33260974, 2020). "And the interaction between CD24 expressed by hepatoma cells and Siglec-10 expressed by NK cells may be beneficial for tumors to escape the killing effect of NK cells and promote tumor immune escape." (PMID 32765491, 2020). "Therefore, the interaction between CD24 and Siglec-10 inhibits the phagocytosis of macrophages, so that the tumor cannot be cleared by phagocytosis, which promotes the immune escape of tumors." (PMID 32765491, 2020). "CD24, a small glycophosphatidylinositol-anchored cell surface receptor, is overexpressed in approximately 70% of solid cancers, and has been proposed as a prognostic and therapeutic tumor-specific biomarker for EOC." (PMID 33260974, 2020). "HIF-1a induces the expression of CD24 at the transcriptional level to promote tumor immune escape, and the non-coding RNA, Wnt/ β-catenin, promotes or inhibits the expression of CD24 to promote or inhibit tumor immune escape." (PMID 32765491, 2020). "It has been suggested that cells designated CD24- using flow cytometry maybe expressing CD24 in the nucleus and this promotes aggressive tumour properties, since it has been shown that nuclear CD24 is able to drive tumour growth." (PMID 32909943, 2020).
tumor (continued). "Four CD24-driven mechanisms have been described that indicate its role in carcinogenesis, and therefore might explain its tumor-specific expression." (PMID 33260974, 2020). "To investigate whether CD24 is overexpressed in patient RB tissues, we examined its expression by IHC in 14 primary RB tumor samples and 6 normal eye tissue samples." (PMID 32394616, 2020). "More importantly, FACS analysis for the CD44-CD24 markers revealed that administration of the LSD1 inhibitor resulted in a significant reduction in the number of tumor CSCs (CD44+CD24-/low), compared to tumors before treatment initiation and to vehicle-treated ones." (PMID 31627418, 2019). "Furthermore, we performed CD24 staining to demonstrate CD24 localization in tumor cells and noted various staining patterns with respect to staining intensity." (PMID 31614769, 2019). "A small population of cells that were CD44+/CD24- formed tumor spheres." (PMID 31612865, 2019). "In addition, EpCAM, CD44, and CD24 have been reported to be relevant for tumor progression and metastatic processes." (PMID 31261643, 2019). "The accumulation of CD24+ cells in solid tumors may provide insight for designing new drugs in order to treat tumor subpopulations." (PMID 30728024, 2019). "A critical finding was that DAXX is a tumor suppressor that may regulate the biological mechanism through the CD24 or β-catenin pathway in patients with CRC." (PMID 31614769, 2019). "The further decrease in the expression of CD24 and up-regulation of JAG1 following AnxA6 down-regulation suggest that reduced expression or loss of AnxA6 is associated with poorly differentiated, highly proliferative tumor cells." (PMID 30719209, 2019). "In addition to free-floating cytokines, tumor cells in ascites are exposed to exosomes from other tumor cells, bearing proteins such as CD24 and the pro-apoptotic proteins Fas ligand and TRAIL." (PMID 31366178, 2019). "Signal of activity was defined as a ≥20% reduction of CSC (defined by either the ALDH+ or CD24−/CD44+ phenotype) in tumor tissue from baseline values as measured by flow cytometry accompanied by a consistent reduction of the same cell population by immunohistochemistry (IHC)." (PMID 30788286, 2019). "Both CD24+ and CD24- cells were capable of initiating tumorigenesis although CD24+ cells gave rise to tumours at a faster rate and with lower numbers of transplanted cells, implying that CD24 expression may be correlative with tumour propagation." (PMID 30657775, 2019). "Furthermore, treatment with DSF/Cu or BKM120 induced higher levels of apoptosis in ALDH+ or CD44+/CD24− populations, respectively, than in bulk tumor cells." (PMID 30659204, 2019). "The CD24/P-selectin binding pathway may affect tumor cell interaction with platelets or endothelial cells in vivo to drive metastasis." (PMID 30467381, 2019). "The binding of CD24 to P-selectin facilitates tumor cell survival and dissemination." (PMID 30717444, 2019). "However, considering the in vivo situation, because CSCs are hidden deep within tumors, it is likely to be important to kill bulk tumor cells (CD24+ cells in this case) and effectively deliver photosensitive agents to the site where CSCs exist." (PMID 31787847, 2019). "Cell surface CD24 has been shown to contribute to tumor metastasis and Src oncogene activation." (PMID 31244889, 2019). "Interestingly, the vast majority of cells in tumours resulting from the CD24- injections were CD24+ implying that the CD24- cell is capable of giving rise to CD24+ cells in vivo." (PMID 30657775, 2019). "For example, expression of the marker CD24 has been used to distinguish between different cancer cell phenotypes, where enhanced tumor-initiating potential correlates with residence in a CD44HiCD24Lo state and the CD44HiCD24Hi cell state is further associated with tolerance to chemotherapy." (PMID 31623163, 2019).
tumor (continued). "The protein expression of CD24 was verified by both western blot and IHC staining, and the results indicated that CD24 was highly expressed in human HCC tissues especially in tumor cells, and that sorafenib-resistant cells expressed significantly higher levels of CD24." (PMID 29844385, 2018). "However, there was a significant increase in the numbers of the CD44+ cells in the hypoxic (EGFP+) MCF7 tumor cell population with the predominant increase of the CD44+/CD24+ population." (PMID 29510720, 2018). "Tumor-initiating cells are enriched in the CD44+/CD24–/low cell population." (PMID 30367042, 2018). "The increased tumour growth of PC-3 cells with endogenous PLA2R1 expression in vivo could therefore indicate PLA2R1 effects in CD44+/CD24- subpopulation that require further confirmation." (PMID 30542512, 2018). "Three of the luminal markers KRT7, KRT19 and CD24 showed staining in the tumor transplants." (PMID 30550540, 2018). "First, we found that the expression of CD24 was higher in the tumor tissues than adjacent tissues; moreover, the clinically diagnosed sorafenib-resistant tumor tissues (n = 13) expressed higher levels of CD24 compared to the non-sorafenib-resistant tissues (n = 57)." (PMID 29844385, 2018). "Furthermore, the high-CD24-expressing cells grew faster and generated larger tumours than the low-CD24-expressing cells after subcutaneous injection of 1 × 104 cells per flank into NSG mice." (PMID 30327565, 2018). "We found increased expression of CD24 in the tumor tissues by western blot, indicating that CD24 might be associated with sorafenib resistance in vivo." (PMID 29844385, 2018). "CD24 was overexpressed not only in primary tumours but also in urine from UCB subjects." (PMID 30327565, 2018). "However, there are several plausible explanations for such a prometastatic role of CD24 expression in human tumor cells." (PMID 29416796, 2018). "However, in different tumors or changing tumor incidence environments, there are various effects of CD24 and diverse activation of its downstream signals." (PMID 29844385, 2018). "Sca-1+CD24+ cells formed organoids at a higher rate than other primary tumor populations (5.8 vs. 3.1, 3.3, and 1.9%, P = 0.002, P = 0.0007, P = 0.0002, t test), demonstrating that more efficient in vitro organoid formation correlates with a TPC-enriched population." (PMID 30455465, 2018). "Also, it can be used to identify the tumor cells with higher expression of CD24 at the early stages more efficiently compare to the other routine methods." (PMID 30607332, 2018). "In addition, the AT1-tumor always exhibited the largest amount of potential stem cells (i.e. CD24+/CD45− cells)." (PMID 29121984, 2017). "The high-level expression of CD24 has been correlated with the degree of tumor progression." (PMID 28360912, 2017). "The CD44+CD24+ESA+ cells as a reflection of stemness is generally confirmed with the fact that cells enriched for CD44+CD24+ESA+ were far more tumorigenical than other tumor cells." (PMID 28245823, 2017). "CD24, an adhesive molecule and one of molecular biomarkers of cancer stem cells, is associated with cancer cell proliferation and migration, and cells with CD24 expression may be the cancer-initiating cells that promote tumor migration and metastasis." (PMID 28968998, 2017). "In agreement with this hypothesis, we have demonstrated the causative role of Aurora-A in promoting the expansion of CD44+/CD24-/ER- BTICs responsible for the onset of distant metastases in vMCF-7∆Raf1 tumor xenografts." (PMID 29207686, 2017).
tumor (continued). "Indeed, Terence and the colleagues reported that CD24+ liver tumor-initiating cells drive self-renewal and tumor initiation through STAT3-inducing NANOG expression, indicating that STAT3 signaling played important roles in the maintenance of CSCs in HCC." (PMID 28750679, 2017). "Moreover, we evaluated the expression of CD44 and CD24 in those murine tumour samples to assess the co-expression of EMT markers and surrogate markers associated with a CSC phenotype." (PMID 28388884, 2017). "The chemoresitant tumor cells displayed an enhanced CD24 expression." (PMID 28930164, 2017). "In addition, they contain tumor antigens, the marker for malignancy CD24, the heat shock protein HSP-70, and an unusual surface expression of HSP-90 was demonstrated." (PMID 28360912, 2017). "CD24 is emerging as a marker of malignant cells and an effector of hypoxia-inducible factor (HIF)-1-driven tumor growth and metastasis, although the association of CD24 and CSCs is not uniform." (PMID 28121626, 2017). "To verify this hypothesis, we analyzed chromosomal aberrations, transcriptome changes, and the presence of CD44+CD24- CSCs in different morphological structures: tubular, solid, alveolar, and trabecular structures, as well as discrete groups of tumor cells." (PMID 28977854, 2017). "Afterwards, tumours were stained against Six1, CD24 and CD44." (PMID 28388884, 2017). "What is more, most of the CD24-positive exosomes are secreted by tumor cells." (PMID 28506269, 2017). "Our findings on tumor specimens from the clinic further supported that CD24 may be an important prognostic factor for TNBC patients who receive taxane-based treatment." (PMID 28418843, 2017). "CD24 is a glycosylphosphatidylinositol-anchored cell surface protein which is expressed mainly on epithelial and neural cells and strongly promotes cell adhesion, tumor growth and metastasis." (PMID 28369074, 2017). "Taken together with independent research, this evidence suggests the hypothesis that selective changes in CD24 expression may regulate the drug sensitivities of tumor cells in part through modulation of cellular autophagy status." (PMID 28418843, 2017). "We found that CD24 is expressed during tumor development in all three models." (PMID 26978528, 2016). "Both CD24+ and CD24− cells led to tumor formation after subcutaneous injection." (PMID 27203385, 2016). "Different from CD44, CD24 was predominately expressed in advanced NPC tumors, which implies that CD24 may be involved in advanced tumor progression." (PMID 27521216, 2016). "In this study, we determined whether the cell surface expression of CD24 may serve as a valuable biomarker for tumor sensitivity to anti-IGF1R therapy." (PMID 27179633, 2016). "Recent studies showed that CD24 was involved in tumor progression including angiogenesis." (PMID 27494878, 2016). "A future challenge will be to understand the mechanistic underpinnings and factors that regulate the localization and translocation of CD24 within the cellular compartments, which may lead to novel therapeutic strategies targeting tumor differentiation." (PMID 27203385, 2016). "Therefore, 100, 1000 or 4000 TICs, as well as corresponding numbers of non-CD24+CD90+ tumor cells, were transplanted into the fat pad of either the right or the left fourth mammary gland of immunodeficient Rag2−/− γc−/−female mice." (PMID 27542270, 2016). "CD24 showed intense staining of cell membranes in both inflammatory and tumor tissues." (PMID 27647953, 2016). "Expression of CD24 in tissue near tumor cells was found in 30% of available samples." (PMID 27099673, 2016). "However, differentiated tumors with ductal lesions arose only from CD24+ tumor cells and these tumors only expressed active β-catenin." (PMID 27203385, 2016). "Live, singlet, Linneg/CD31neg tumor cells were sorted based on expression of CD49f and CD24." (PMID 27001172, 2016).
tumor (continued). "In addition, the observation that CD24 is mainly expressed in the cytoplasm of tumor cells in endogenous GEMMs suggests that surface CD24 expression is transient during PDAC development." (PMID 27203385, 2016). "As expected, CD24+ control cells displayed high tumor-forming efficiency." (PMID 27179633, 2016). "In order to further investigate whether CD24 cell surface expression could implicate tumor sensitivity to anti-IGF1R therapy, we inoculated CD24- and CD24+ cells with and without IGF1R-KD into the mammary fat pad of WT and the hyperinsulinemic MKR female mice." (PMID 27179633, 2016). "The expression of CD44 and CD24 are highly positive correlation with tumor stage." (PMID 27521216, 2016). "RNA was isolated from freshly sorted TICs and non-CD24+CD90+ tumor cells." (PMID 27542270, 2016). "A Principle component analysis (PCA) of the transcriptome data revealed a separation of TICs and non-CD24+CD90+ tumor cells along the first principle component (34.6%), indicating that these are indeed two distinct cell populations with different gene regulation." (PMID 27542270, 2016). "We also detected the other screened proteins, such as Grp75 and Hspa8/Hsc71 by coimmunoprecipitated with CD24, and found that these two proteins were also interacted with CD24, but no evidences suggested that both two proteins were involved in tumor angiogenesis." (PMID 27494878, 2016). "In tumor cells, CD24 was expressed in the cytoplasm of integrin-β3-negative cells." (PMID 27203385, 2016). "To determine the extent to which our basic staining panel could be used to identify specific subtypes of TAMs, we examined the expression of our other staining panel markers on the CD64+ CD24- macrophage population in each tumor." (PMID 26938654, 2016). "Therefore, the expression levels of CD24 can indicate the levels of sensitivity to cisplatin one can expect in a tumor." (PMID 27276062, 2016). "However, while assessing the expression of CD133, CD44 and CD24 in primary tumor CRC tissue and in SC derived from patient material, we observed a very heterogeneous expression." (PMID 26745821, 2016). "Thus, CD24+CD90+ tumor cells are not only tumorigenic, but also metastatic and represent a metastatic TIC population in the MMTV-PyMT model, which is in line with other work on CD24+CD90+ TICs." (PMID 27542270, 2016). "This transient surface localization could also explain the small number of tumor cells expressing surface CD24 that can be sorted from human tumors." (PMID 27203385, 2016). "Please note that non-CD24+CD90+ tumor cells showed extremely low frequency of colony formation." (PMID 27542270, 2016). "Accordingly, CD24-expressing cells possess tumor initiating properties in this model." (PMID 26978528, 2016). "CD24 is a ligand for endothelial cell P-selectin, suggesting that it may act in metastatic dissemination of tumour cells, and it has been shown to promote both tumour cell invasion and metastasis." (PMID 26981578, 2016). "Two mice developed tumors resulting from 1000 non-CD24+CD90+ tumor cells." (PMID 27542270, 2016). "Tumor cells in these sections showed positive staining for CD24." (PMID 26449187, 2015). "The number of tumor spheroid formations of cancer stem like CD44+/CD24- cells delivered from MDA-MB-231 cells was significantly reduced after carbon ion beam compared to X-ray irradiation, and it was extremely decreased when the carbon ion beam combined with CDDP." (PMID 26338199, 2015). "Therefore, CD24-positive cells probably attach to activated platelets, containing P-Selectin on their surface, at the point, when the primary tumour invades into the vascular system." (PMID 26578846, 2015). "However, progenitor cancer cells with the ability to initiate new tumours express lower levels of CD24 than differentiated cells." (PMID 25864518, 2015).